EGFR (epidermal growth factor receptor)
Diseases named in the same sentence as EGFR in open-access papers (continued):
Sharing a sentence is not in itself a finding about the gene and the disease.
tumor (continued). "Cetuximab, which is FDA-approved mAb to treat a variety of human cancers, binds to the extracellular domain of EGFR, and mediates its anti-tumor properties by apoptosis induction, cell-cycle arrest, metastasis inhibition, antibody and complement-mediated cytotoxicity." (PMID 33804477, 2021). "PD-L1 mediated by EGFR activation could induce the apoptosis of T cells through PD-L1/PD-1 axis in tumor cells." (PMID 34503172, 2021). "Osimertinib potentially may inhibit neoplasm growth in EGFR-overexpressing tumor cells and induce cell death." (PMID 34439273, 2021). "In conclusion, although osimertinib combined with crizotinib showed dramatic tumor shrinkage both in primary tumor and bone metastasis in EGFR T790M-mutant NSCLC patients with MET amplification, more studies should be performed to confirm the clinical benefit in PFS and overall survival." (PMID 34397683, 2021). "In this case, pharmacological inhibition of EGFR, restored T-cell presence in tumour stroma." (PMID 33671588, 2021). "Changes in tumor glucose metabolism precede decreases in tumor size in response to EGFR TKIs." (PMID 34155348, 2021). "Moreover, an anti-EGFR Nb-cucurmosin immunotoxin was shown to inhibit the cell viability of EGFR-expressing tumor cell lines as well as induce HepG2 and A549 apoptosis." (PMID 34575943, 2021). "Moreover, EGFR inhibition shall have a direct antitumor effect mediated by the blockade of the tumor proliferation and apoptosis induction." (PMID 34211836, 2021). "Moreover, simultaneous EGFR-targeted NIR-PIT with CD25-targeted NIR-PIT inhibited tumour growth and prolonged survival compared to monotherapy in allografted mouse models." (PMID 34332294, 2021). "Moreover, IL-22 has been shown to induce gefitinib resistance both in vitro and in vivo, indicating that IL-22 induction within the tumor microenvironment complicates the acquired EGFR-TKI-resistance in NSCLC." (PMID 33466795, 2021). "Overexpression of HER2 alone, or in co-overexpression with EGFR, could enhance down regulation of EGFR tyrosine kinase activity and induce aggressive tumor growth." (PMID 39035769, 2021). "In-vitro studies showed that the non-inflammatory tumor microenvironment (TME) changed in EGFR-mutated NSCLC after partial drug intervention, improving the efficacy of immunotherapy." (PMID 34178613, 2021). "On the other hand, immune cells within the tumor microenvironment may also account for EGFR-TKI resistance." (PMID 33964931, 2021). "Other occasionally reported factors included tumour distribution (peripheral or central), pneumonectomy, plasma albumin concentration, NSE concentration, C-kit protein expression, Nestin expression and EGFR mutation." (PMID 33579331, 2021). "In addition, Notch3 signaling also contributes to tumor chemoresistance against several drugs, including doxorubicin, platinum, taxane, epidermal growth factor receptor (EGFR)–tyrosine kinase inhibitors (TKIs) and gemcitabine, through complex mechanisms." (PMID 34195229, 2021). "Yet, in right-sided tumor, anti-EGFR therapy arm induced worse QALY than Bev arm." (PMID 34012917, 2021). "Tumor heterogeneity is thought to play a role in TKI response and is associated with poor outcome, as EGFR mutations may be suboptimal targets when they co-occur with genetic alternations or are subclonally expressed." (PMID 33976268, 2021). "Increased expression of CD200 in tumor was associated with female sex, never-smoking status, adenocarcinoma histology, early disease stage, and EGFR mutations." (PMID 33804482, 2021). "These growth factors bind with high affinity to their cognate tyrosine kinase receptors (VEGFR, EGFR, FGFR, and PDGFR), which play pivotal roles in angiogenesis, tumor growth, and survival, and are associated with poor prognosis, high metastasis, and lower overall survival and disease-free survival." (PMID 33805447, 2021).
tumor (continued). "Serum tumor markers, such as CEA, SCCA, CYFRA 21-1, NSE, and ProGRP, are considered to be predictive or prognostic in NSCLC, and some of these markers have been shown to be correlated with EGFR mutations." (PMID 34422624, 2021). "Furthermore, combination treatment with AKIs and EGFR inhibitors has been found to robustly decrease tumor growth in an EGFR-mutant LUAD PDX model." (PMID 33451333, 2021). "In this study, we conduct a thorough explorative analysis of cancer-related genes through NGS of tumor tissues from the EGFR-mutant patients of the ADJUVANT trial, in an attempt to address important co-mutations and identify key predictive biomarkers for adjuvant treatment." (PMID 34750392, 2021). "But, patients with wild-type KRAS tumours can be treated with bevacizumab or anti-EGFR therapy." (PMID 34557315, 2021). "In terms of inhibiting cell migration and in consequence spread of tumor cells, a combination approach of EGFR and TGFβ-receptor inhibitors could be more effective." (PMID 33777943, 2021). "Furthermore, many reports have emphasized that the EGFR and SHH signaling pathways are also upregulated in ACPs and are associated with tumor cell migration." (PMID 34707096, 2021). "The NF2 tumor suppressor gene encodes Merlin (Moesin-ezrin-radixin-like protein), which mediates tumor suppression and contact-dependent inhibition by repressing Hippo, mTORC1, RAS, EGFR, and FAK-Src signaling pathways." (PMID 33859162, 2021). "In addition, in patients with RAS wildtype disease, the benefit derived from anti-EGFR antibodies is far greater in left-sided than right-sided primary tumours." (PMID 34407800, 2021). "Persistence of EGFR amplification and ECD missense mutations in the context of loss of EGFRvIII expression suggested that tumor heterogeneity played an essential role for tumor recurrence and continued regrowth." (PMID 34568006, 2021). "The transcription factor, STAT5a/b, which is immediately downstream of EGFR Y845, also showed a significant decrease in phosphorylation at tyrosine positions 694 and 699 in both adjacent normal (P = 0.004) and tumor (P = 0.01) tissue samples from Anthos-treated animals." (PMID 34926717, 2021). "In triple-negative breast cancers (TBNCs), which are very aggressive tumors characterized by the lack of ER, progesterone receptor (PR), and HER2, high expression and reciprocal compensation between β1 integrin and EGFR signaling synergize to support tumor progression and metastasis." (PMID 34131655, 2021). "In addition, EGFR-mutant brain metastatic animal experiments revealed a significant decrease in tumor volume in AZD3759-treated mice." (PMID 34635007, 2021). "In addition, these NPs enabled the redirecting of T cells specifically to cancer cells through dual decoration of an Ab targeting epidermal growth factor receptor (EGFR) expressed by tumor cells." (PMID 34930494, 2021). "In this review, we have summarized the results of the studies on the combination of Fu-nCRT with cytotoxic drugs, anti-tumor angiogenesis, and anti-EGFR agents, as well as the status of the application of immune checkpoint inhibitors in the neoadjuvant therapy of LARC patients." (PMID 33391438, 2021). "The Western blot assay with tumor cell lysate proved the down-regulation of EGFR protein." (PMID 34959463, 2021). "Moreover, 19 (13.9%) patients had wt EGFR detected in tumor tissue, and all tested wild-type in liquid biopsy." (PMID 34680416, 2021). "Eleven patients showed EGFRm only in the ctDNA (tumor DNA EGFR wild‐type or unknown, Group A) and 10 exhibited the same EGFRm in both their ctDNA and tumor DNA (Group B)." (PMID 33270375, 2021).
tumor (continued). "Consistent with the ELISA results, confocal images showed that the repebody rEgH9 can specifically recognize target cancer cells in an EGFR-dependent manner and revealed that the repebody with a smaller KD value has a higher binding ability to target antigens displayed on the tumor cell surface." (PMID 33615202, 2021). "We speculate that Shan Ci Gu may play a role in inhibiting tumor cell proliferation by targeting several proteins such as EGFR, SRC, and ESR1 in NSCLC." (PMID 34178945, 2021). "Furthermore, some tumor-promoting ECM components (e.g., glycoproteins and proteoglycans) enhance activation of EGFR and loss of PTEN." (PMID 34976811, 2021). "Specific tumor homing was ensured by using EGFR-tailored EDVs." (PMID 34072348, 2021). "This study showed that although each patient had positive mutations in driver Genes, the rate and degree of tumour volume shrinkage after EGFR-TKI treatment were not consistent." (PMID 34631535, 2021). "A blockade of EGFR activation significantly ameliorates tumor-induced angiogenesis." (PMID 34680445, 2021). "However, when analysed according to treatment received in this cohort, patients with EGFR CNG positive tumours who received neoadjuvant PBC had longer overall survival than patients with EGFR CNG positive tumours who did not receive neoadjuvant PBC." (PMID 33169187, 2021). "Targeted treatment of EGFR-mutated non-small cell lung cancer may trigger an increase in TMB and an increase in tumor PDL1 expression." (PMID 33498238, 2021). "More interestingly, the administration of Visudyne, an FDA-approved form of Verteporfin, in patients with suspected or known recurrent GBM showed its absorption in GBM tumor cells, suggesting the use of Verteporfin as a promising therapeutic agent for EGFR-amplified/mutant GBM." (PMID 33477668, 2021). "Finally, ZEB1, BMI1, and ALDH1A1 were highly expressed in tumor specimens from EGFR‐mutant NSCLC patients with gefitinib resistance." (PMID 33764690, 2021). "Overall, these data showed that miRNA-regulated EGFR could differentially affect tumor growth, proliferation, invasion, and metastasis." (PMID 34830377, 2021). "Overexpression of ST3Gal1 has been shown to promote tumor cell migration and metastasis, which may involve epidermal growth factor receptor (EGFR) signaling, or receptor tyrosine kinase AXL dimerization/activation." (PMID 34975914, 2021). "Previous studies have reported that first- and second-generation EGFR TKIs have poor penetration across the blood–brain barrier, with the percentage of drug penetration ranging between 0.7% and 1.3%, which may permit tumor growth in the central nervous system." (PMID 35127465, 2021). "MSA could downregulate EGFR via miR-146a and decrease IL-6 secretion, lead to substantial decrease in tumor angiogenesis to inhibit ESCC cell growth." (PMID 34393797, 2021). "Here, we defined wt LUADs as tumours with diploid copy numbers and no identifiable EGFR mutations or copy number variations." (PMID 35052732, 2021). "Interestingly, the combination of HU5F9-G4 with cetuximab or panitumumab (anti-EGFR mAbs) reduces tumor burden more than any of the monotherapies in immunodeficient mice harboring patient-derived xenografts." (PMID 34572847, 2021). "Recent studies have shown that EGFR regulate migration, tumor invasion and EMT." (PMID 33802438, 2021). "In addition, the cancer markers alpha-fetoprotein, tumor marker, S (0.78%) and epidermal growth factor receptor (EGFR) (1.56) were found to be the main contributors for the prediction of cancers of the liver and bronchus and lung." (PMID 34032581, 2021).
tumor (continued). "In this regard, the clinical application of EGF treatment may be a possible approach to reduce the excessive activity of EGFR in inducing tumor proliferation." (PMID 33898431, 2021). "Thus, a suitable therapeutic strategy can be built upon a comprehensive understanding of the mechanism of action of EGFR and its impact on tumor development." (PMID 34943898, 2021). "Similarly, the application of an anti-EGFR Ab to AOM/DSS-treated mice fed a GFHPD significantly reduced the presence of large tumors with a tumor score of 5 (27.3%) when compared to ctrl." (PMID 34830971, 2021). "Yiqi formula inhibited the TNBC xenograft tumor growth by reducing p-EGFR and p-AKT1." (PMID 34225726, 2021). "Neither tumor nor stromal expression of CD200 or CD200R demonstrated significant associations with epidermal growth factor receptor (EGFR) or KRAS mutation status in NSCLC patients." (PMID 33804482, 2021). "These alternative pathways may trigger intracellular signaling pathways to bypass EGFR and induce tumor cell growth and proliferation, leading to resistance to anti-EGFR therapies." (PMID 34884633, 2021). "Multiple mechanisms can trigger tumor resistance to EGFR-targeted therapy." (PMID 34568049, 2021). "Collectively, the downregulation of miR-155-5p may enhance the anti- tumor effect of cetuximab in EGFR-overexpressed TNBC cells in vitro and in vivo by inducing pyroptosis." (PMID 33472170, 2021). "Thus, our study identified novel mechanisms for ILT4-mediated tumor immune escape in EGFR-activated NSCLC and suggested promising immunotherapeutic and combination strategies for these patients." (PMID 33537094, 2021). "In addition to its canonical function in promoting EGFR activation on cancer cells, it also has the ability to influence the composition of the tumor microenvironment." (PMID 34843542, 2021). "The other line of research, as highlighted by recent findings, suggests that the overexpression, specifically of mutant forms of the EGFR, may create an immune-suppressive and lymphocyte depleted microenvironment within tumours." (PMID 35052732, 2021). "As a tumor suppressor gene, RB1 is mutationally inactivated in around 10% of EGFR mutant LUADs." (PMID 34944063, 2021). "To confirm the reduced abundance of CXCL13+CD4+ T cells in EGFR-MT compared with EGFR-WT tumor, inferred from the single-cell transcriptome analysis, we performed the multiplexed immunofluorescence (IF) staining in archival tissue specimens of the same samples." (PMID 34663810, 2021). "Third, despite developing EGFR-TKI resistance, the tumor/s of patients detected with concurrent EGFR mutation and MET amplification at disease progression have acquired “addiction” to MET but remains “addicted” to EGFR." (PMID 34660287, 2021). "EGFR expression levels vary over orders of magnitude between cell types and are commonly elevated in tumor cells, so it is important to know whether simply altering EGFR expression is sufficient to override stiffness-related modulation." (PMID 34965432, 2021). "Thus, future studies using primary tumor specimens are highly warranted to unravel the complex interplay of hypoxia, cell-intrinsic EGFR-signaling, and PD-L1 expression to optimize multimodal antineoplastic strategies." (PMID 33718186, 2021). "Molecular profiling implicated EGFR as a likely mediator of enhanced tumor growth in the absence of ERBB3." (PMID 34843459, 2021). "In summary, our preclinical studies show that HER2 or EGFR hCART41BBζ can effectively kill multiple tumor targets, kill tumor targets in sequential and serial killing assays, secrete Th1 cytokines and chemokines and exhibit specific target killing in in vitro hypoxic condition." (PMID 34290709, 2021). "While there were no clear associations of the EGFR tumor shedding status with sex, race, smoking status and performance status according to Eastern Cooperative Oncology Group (ECOG), an association with the baseline tumor target lesion size has been reported." (PMID 34202063, 2021).
tumor (continued). "Univariate analysis of the TCGA dataset suggested that age (P = 0.003), history of colon polyps (P = 0.020), tumor stage (P < 0.001), mismatch repair system (MMR) status (P = 0.045), EGFR mutation (P = 0.003), and risk score (P < 0.001) were significantly associated with OS." (PMID 34898475, 2021). "Fcy-hEGF fusion protein, composed of yeast cytosine deaminase (Fcy) and human EGF (hEGF), is capable of binding to EGFR and enzymatically convert 5-fluorocytosine (5-FC) to 1000-fold toxic 5-fluorocuracil (5-FU), thereby inhibiting the growth of EGFR-expressing tumor cells." (PMID 33672989, 2021). "They identified one patient (9.1%) with EGFR amplification: ≥ 4 copies in ≥ 40% of tumor cells." (PMID 34851968, 2021). "However, GBM tumor cells usually maintain EGFR signaling activity even under EGFR inhibition treatment, and strategies targeting EGFR have failed in clinical trials." (PMID 33959491, 2021). "Importantly, the expression of Tspan6 in CRC correlated independently of tumor molecular profile with better patient responses to Cetuximab, an EGFR-targeted therapy." (PMID 34521767, 2021). "Taken together, these results indicate that TTP directly controlled Areg mRNA stability in keratinocytes, and that dysregulated EGFR signaling may contribute to exacerbated tumor formation in Zfp36ΔEP mice." (PMID 33497366, 2021). "The non-inflammatory tumor microenvironment (TME) in EGFR-mutated NSCLCs is abundant in Treg cells and macrophages, with the latter releasing chemokines that attract more Treg cells in the inflammatory TME." (PMID 34447695, 2021). "This effort was achieved through the use of three tumor cell lines (A431, AsPC-1, and 9L) with varying EGFR expression levels, alongside benign adipose tissue to ensure retention of similar tumor-to-adipose (T/A) contrast, which is required for successful margin assessment during BCS." (PMID 33882909, 2021). "Previous studies have shown that levels of cfDNA shedding into plasma correlate with the tumor burden, and the lack of detectable cfDNA early in EGFR-TKI therapy is associated with better clinical prognosis." (PMID 34638411, 2021). "Tumour cell exposure to irinotecan leads to resistance through upregulation of EGFR signalling." (PMID 34253874, 2021). "When uPAR was silenced or EGFR was knocked down, geftinib resistance could be overcome and tumor cell apoptosis occurred via the EGFR/p-AKT/survival signaling pathway." (PMID 33669052, 2021). "Based on the known background sensitivity of EGFR, deletion of both Egfr and Erbb3 on a C57BL/6J background showed a dramatic decrease in polyp number indicating the tumor increase with loss of ERBB3 on the C57BL/6J background was at least partially mediated by EGFR." (PMID 34843459, 2021). "On the one hand, the use of the EGFR-CD16 bispecific VHH could be extended to other EGFR expressing tumor types." (PMID 34771609, 2021). "Furthermore, as panobinostat has been shown to destabilize EGFR, for both tumor types it cannot be excluded that this also leads to conformational changes in the kinase domain which increase sensitivity to erlotinib." (PMID 34281526, 2021). "It is reported that dysregulation of AXL expression is very common in the resistance of tumor cells to EGFR TKIs, the up-regulation of AXL can be detected after the first generation EGFR TKIs gefitinib, erlotinib 31 and the third generation EGFR TKI Osimertinib 32 acquired resistance." (PMID 34335945, 2021). "Therefore, the improved technique was also testedon sEVs isolated from PE-fluid samples of two NSCLC patients, PE002and PE011, having an ALK and EGFR-driven tumor, respectively." (PMID 34473477, 2021). "CD16 in tumor conditions binds to EGFR and leads to tumor cell proliferation." (PMID 33763348, 2021).